GCG (glucagon)
Diseases named in the same sentence as GCG in open-access papers (continued):
Sharing a sentence is not in itself a finding about the gene and the disease.
Obesity (continued). "Clearly, the liver is pivotal in mediating glucagon’s anti-obesity effects, but the contribution of other organs remains to be determined." (PMID 31671603, 2019). "Obesity (and malnutrition) has been suggested as a potential inducer of glucagon resistance in animal models, but to what extent this is recapitulated in humans is not yet clear." (PMID 31284506, 2019). "In our recently published manuscript, we have shown that the oral and topical administration of menthol, a TRPM8 agonist, has anti-obesity potential through a TRPM8 mediated glucagon dependent mechanism." (PMID 31027377, 2019). "Several clinical studies are currently investigating the potential treatment of obesity and T2D using glucagon/GLP-1 co-agonists." (PMID 31068828, 2019). "Our results suggest the involvement of lipid metabolism, glucagon and insulin signaling pathways in obesity-driven alterations of adipocyte functions related to carcinogenesis." (PMID 30838002, 2019). "As we commented on before, another study evaluated the effect of glucagon on body weight in Zucker rats, a genetic model of obesity that exhibit decreased release of glucagon from pancreatic islets, as a consequence of leptin receptor mutation." (PMID 31405212, 2019). "The most promising approach to use glucagon as a therapy against obesity comes from its combination with other hormones." (PMID 31405212, 2019). "•Peptides are being developed which combine activation of glucagon and incretin receptors to treat obesity." (PMID 29412829, 2018). "As such, there is interest in developing glucagon-GLP-1 co-agonists (i.e. an oxyntomodulin analogue) to treat obesity." (PMID 29412829, 2018). "It will be necessary to design specific studies to try to clarify insulin–amylase–glucagon relations in health and obesity." (PMID 30293998, 2018). "Circulating insulin levels are elevated in each model of obesity, while glucagon was increased only in the db/db mice." (PMID 29038790, 2017). "Diet-induced obesity abolished the anorectic effects of GCG but it was restored by molecular inhibition of CaMKKβ in the ARC via adenoviruses encoding dominant negative CaMKKβ." (PMID 28223965, 2017). "The ability of chronically elevated palmitate levels to simultaneously increase basal secretion of glucagon and insulin positions elevated levels of fatty acids as potential triggering factors for the development of obesity and impaired glucose control." (PMID 28680093, 2017). "With increasing BMI of ND subjects, insulin and glucagon contents respectively tended to increase and decrease, resulting in a lower glucagon/insulin ratio in obesity." (PMID 28887444, 2017). "The anorectic action of glucagon is an issue that makes this hormone attractive as a pharmacological target to treat obesity." (PMID 26909312, 2015). "Our next candidate to explain the obesity-induced hypothalamic resistance to the anorectic action of glucagon was CaMKKβ." (PMID 26909312, 2015). "Future studies are needed to determine if obesity plays a role in altering pancreatic α2‐adrenoceptor activation after hemorrhage, resulting in exaggerated suppression of both insulin and glucagon secretion." (PMID 25472607, 2014). "However, under stress, obesity may cause alterations in glucagon regulation." (PMID 25472607, 2014). "OXM can inhibit food intake, elevate metabolic rate, and cause weight loss when administered peripherally in humans, sparking interest in the use of OXM or related glucagon-GLP-1 receptor co-agonists as a potential therapy for obesity." (PMID 24303183, 2013). "It was reported that absence of glucagon signaling was associated with decreased body weight and food intake in GCGR knockout (Gcgr−/−) mice when HFD was challenged, implying a protective role of glucagon antagonists as anti-obesity agents." (PMID 23226550, 2012).
Obesity (continued). "In this study, BMI was taken as major criteria of obesity and correlation of BMI with different clinical and genetic parameter was seen like waist to hip ratio and hormonal levels (insulin, leptin, glucagon, and growth hormone)." (PMID 20300294, 2008). "Skipping breakfast and eating large dinners affects the way the tissues respond to the influence of insulin and glucagon, ultimately facilitating resistance, a key problem in the development of metabolic syndrome and other obesity-related problems." (PMID 17875273, 2007). "Similarly, we have shown that the hepatic expression of SLC7A2 was downregulated in individuals with obesity and glucagon resistance to amino acid catabolism, although fasting arginine concentrations were similar compared to lean individuals." (PMID 40980546, 2025). "Given the hyperglycaemic effect of GCG, it might seem counterintuitive to use GCG agonism in people living with obesity." (PMID 40892365, 2025). "In a study comparing glucose turnover in response to a glucagon infusion between lean volunteers and patients with obesity, endogenous glucose production and rate of glucose disappearance were higher at baseline in lean subjects (due to greater insulin sensitivity)." (PMID 38579751, 2024). "Inadequate suppression of glucagon during an EHC also occurs in adolescents with obesity and IGT." (PMID 38087928, 2024). "Resveratrol was also found to suppress postprandial glucagon in subjects with obesity, which could contribute to reduced glucose levels." (PMID 38732542, 2024). "Findings from this study suggest that insulin resistance is coupled to the obesity-related alterations in glucagon and GLP-1 secretion, which could have important implications for future disease risk." (PMID 38087928, 2024). "Although there are few studies of the effects of glucagon infusion in patients with obesity and/or MASLD, there is some evidence that the expected effect of glucagon on amino acid catabolism may be attenuated." (PMID 38579751, 2024). "More recently, clinical trials involving drugs that combine GLP-1 receptor agonism with agonism or antagonism of other receptors, such as those for GIP or glucagon, have shown considerable promise in the management of T2D and obesity (eg, the triple GLP-1/GIP/glucagon RA, retatrutide)." (PMID 39568409, 2024). "Increased glucagon secretion in obesity is also reported in Caucasians." (PMID 38966210, 2024). "Therefore, it is likely that an attenuation of the impact of glucagon to support postabsorptive endogenous glucose production and glycemia occurs in individuals with T2DM associated with obesity." (PMID 38265288, 2024). "Furthermore, elevated fasting glucagon and impaired suppression of glucagon levels during OGTT are known to occur in individuals with obesity as well as in those with T2D." (PMID 39459592, 2024). "In our cohort of Austrian and Swedish youth with overweight and obesity (and normal weight controls), we were able to thoroughly investigate glucagon in regard to different glycemic states, ranging from normal glucose metabolism to prediabetes (distinguishing between IGT and IFT) and T2D." (PMID 39027470, 2024). "It still remains unclear whether insulin resistance mediates the effects of obesity on impaired glucagon and gut hormone secretion, and whether this occurs early on in disease pathogenesis." (PMID 38087928, 2024). "One process affected by genetic variation and that influences obesity is the glucagon pathway." (PMID 39196987, 2024). "Moreover, children and adolescents with obesity display diminished glucagon suppression during an oral glucose tolerance test (OGTT) or an euglycemic–hyperinsulinemic clamp (EHC), dependent on the level of insulin resistance." (PMID 38087928, 2024).
Obesity (continued). "Glucagon and glucagon-like peptide-1 (GLP-1) are derived from the same precursor; proglucagon, and dual agonists of their receptors are currently being explored for the treatment of obesity and metabolic dysfunction-associated steatotic liver disease (MASLD)." (PMID 38705923, 2024). "Estimation of other insulin and glucagon regulators like somatostatin and incretins could have also been included to give us a wholesome picture of insulin and glucagon secretion in obesity and in different glucose tolerance states." (PMID 38665134, 2024). "Furthermore, the “liver–α-cell axis” links AAs to glucagon secretion, contributing to metabolic imbalances in conditions like obesity and T2DM." (PMID 37764697, 2023). "Obesity can lead to impaired postprandial glucagon secretion." (PMID 36834693, 2023). "Importantly, due to insulin resistance and elevated ratio of glucagon/insulin in obesity and T2DM, lipolysis would be increased in adipose tissue and a glycerol flux to the liver would occur, glycerol will be used as a preferred gluconeogenic precursor." (PMID 36836874, 2023). "Glucagon/GLP-1 dual agonism is considered for the treatment of obesity." (PMID 37140984, 2023). "The role of glucagon secretion in obesity development is currently uncertain, and although its actions on food intake and liver fat may be pharmacologically relevant, its further metabolic actions may be difficult to harness." (PMID 35990325, 2022). "In our study, univariate analysis not only indicated a significant relationship of fasting insulin, VAT, MRI liver fat content with glucagon in our cohort of children and adolescents with overweight and obesity, but also with the liver enzyme alanine transaminase (ALT)." (PMID 36133310, 2022). "However, the extent to which glucagon influences whole‐body lipid metabolism, particularly in individuals affected by obesity, remains controversial." (PMID 34713962, 2022). "Glucagon resistance has previously been reported in patients with obesity and NAFLD but here we demonstrate glucagon resistance in mice fed a cholesterol-rich diet for just seven days, a period sufficiently short to result in no alteration in body weight nor hepatic fat content." (PMID 35718339, 2022). "The degree of obesity has been positively associated with glucagon levels, independent of insulin-resistance and individuals suffering from hepatic dysfunctions display fasting hyperglucagonemia without altered glucose tolerance." (PMID 36686477, 2022). "Notably, FGF21 and the FGF21 receptor complex (FGFR1c and KLB) knockout mouse models indicate that glucagon requires the FGF21 pathway to protect from obesity." (PMID 35547006, 2022). "Importantly, the administration of glucagon is still capable of augmenting metabolic rate following an overnight fast (or state of energy deficit) in adult humans and experimental models of obesity." (PMID 35547006, 2022). "In a pediatric population with obesity and T2D, glucagon-levels showed an early rise during OGTT." (PMID 36686477, 2022). "Early indications of severely lowered diurnal secretion in obesity were obtained with assay for enteroglucagon (crossreacting glucagon antibodies) in people with morbid obesity, and early measurements of total GLP-1 in obese individuals supported this conclusion." (PMID 35990325, 2022). "Preclinical testing of desHis1Glu9-glucagon and desHis1Glu9(Lys30PAL)-glucagon in HFF obese mice reversed obesity-driven hyperinsulinaemia and insulin resistance together with improvements in lipid profile, glucose tolerance and increased pancreatic insulin stores." (PMID 34093449, 2021). "Similarly, in boys with obesity, there was a higher expression of insulin (p <0.0001), leptin (p <0.0001), c-peptide (p < 0.0001), amylin (p = 0.0013), glucagon (p = 0.04), GLP-1 (p < 0.0001), and ghrelin (p = 0.07), compared to the eutrophic group." (PMID 33644105, 2020).
Obesity (continued). "Novel glucagon/glucagon-like peptide-1 (GLP-1) receptor dual agonists and glucagon/GLP-1/glucose-dependent insulinotropic peptide (GIP) receptor triagonists are currently being developed to treat obesity and associated comorbidities." (PMID 32232363, 2020). "Finally, we aim to investigate if dapagliflozin treatment increases insulin and glucagon secretion in patients with obesity." (PMID 32059692, 2020). "The dysregulated hypersecretion of glucagon contributes to dysglycemia in obesity and T2D." (PMID 33353164, 2020). "Apart from this, since obesity is mainly induced by high caloric consumption and that glucagon induces satiety, it is conceivable that this hormone could have an impact on energy metabolism and body weight control." (PMID 31405212, 2019). "However, the pharmacological value of glucagon to treat obesity is nonetheless hampered by glucagon’s hyperglycemic nature." (PMID 31671603, 2019). "Briefly, our data strongly indicate that pharmacological activation of cold receptor TRPM8 by menthol plays an important role in energy homeostasis via activation of glucagon machinery which provides an additional mechanism for TRPM8 activation induced prevention of obesity and related conditions." (PMID 30505271, 2018). "It is therefore likely that abnormal expression of GCG may contribute to the development of obesity." (PMID 28252032, 2017). "Dyslipidemia, dysregulated adipokine secretions and alteration in glucagon and adropin concentrations are important obesity-related factors in the pathophysiology of human T2DM; however, their roles in the pathophysiology of FDM are relatively unknown." (PMID 28376869, 2017). "The cutoff value of 3 μg/L has also been recommended to discriminate between normal response and severe AGHD in the GST13–16,26, but a lower threshold of 1 μg/L was recently proposed for overweight/obese subjects, as obesity blunts GH response to glucagon stimulation." (PMID 29225782, 2017). "In obesity fasting levels of both glucagon and insulin are elevated." (PMID 28680093, 2017). "Therefore, in the present study, we examined the behaviour and morphofunctional features of pancreatic alpha-cells as well as glucagon release during the compensatory adaptation of the islet in a model of high-fat diet-induced obesity." (PMID 26108563, 2015). "Our findings suggest that, in addition to the central resistance to certain hormones regulating food intake, such as leptin or insulin, central resistance to glucagon-induced hypophagia might also contribute to the development of obesity." (PMID 26909312, 2015). "In the obesity-associated factors, FFA and glucagon elevated, but TNF-α decreased IDE protein." (PMID 24740421, 2014). "In our speculation, the association of GLP-1 with higher triglyceride levels may be secondary to increased hepatic synthesis of triglycerides under influence of glucocorticoids, glucagon, and obesity and/or MetS -induced sympathetic nervous system activation." (PMID 20470376, 2010). "Newer anti-obesity medications are being developed that have promise for altering energy expenditure, although these are multi-receptor agonists involving binding both GLP-1 receptors and receptors such as glucagon which has been associated with increased energy expenditure." (PMID 40149944, 2025). "Thus, in recent years it has been proposed that combining GCG agonism with incretin-based agonism could help optimize the pharmacological treatment of obesity." (PMID 40892365, 2025). "Furthermore, an association between the degree of obesity and fasting glucagon levels independent of insulin resistance was detected in nondiabetic subjects." (PMID 40069760, 2025). "However, DR-10,624, a GLP-1/GCG/fibroblast growth factor 21 (FGF-21) triple agonist is under investigation for individuals with severe hypertriglyceridemia (not limited to individuals with obesity; NCT06555640)." (PMID 40741227, 2025).
Obesity (continued). "Other combinations of entero-pancreatic hormones including cagrisema (GLP-1/amylin RA) and the triple agonist retatrutide (GLP-1/GIP/glucagon RA) have also progressed to phase 3 trials as obesity treatments and early data suggests that may lead to even greater WL than tirzepatide." (PMID 38302593, 2025). "To determine the role of glucagon and glucagon-related peptides in type 2 diabetes, and whether hyperproglucagonaemia exists independently of obesity, MASLD and type 2 diabetes, we analysed data from the UK Biobank including data from nearly 500,000 individuals." (PMID 38705923, 2024). "On the other hand, GIGD as the integrated glucose handling capacity encompassing the glucagon inhibitory effect decreases with worsening glucose intolerance and increasing obesity, which may be a common pathophysiologic characteristic between Asians and Caucasians." (PMID 38966210, 2024). "However, the data presented here are consistent with an interpretation that glucagon signalling at the level of hepatocytes may contribute to improving glucose tolerance in the context of obesity and MAFLD." (PMID 39236784, 2024). "Besides genetic defects and pharmacological interventions to inhibit glucagon signaling, hepatic disorders (e.g., NAFLD and NASH) and certain metabolic conditions (e.g., obesity, T2DM) have been associated with impaired glucagon signaling and hence disrupted LACA." (PMID 36686477, 2022). "The synergistic actions of glucagon to reduce food intake and increase energy expenditure, GLP‐1 to reduce calorie intake, and GIP to potentiate bodyweight loss may aid in the treatment of obesity." (PMID 34713962, 2022). "Interestingly, obesity with T2D decreased GCG expression and its transcriptional regulator PAX6." (PMID 33037328, 2021). "Thus, the studies concerning the mechanism of AKHs action in insects might be a source of knowledge that can help better understand the role of glucagon signalization disturbance in development of obesity and other metabolic disorders." (PMID 34681728, 2021). "Furthermore, this information would improve our understanding of the dynamic metabolism-reproductive interface and help determine whether the impact of obesity on the endocrine reproductive axis could be in part mediated through glucagon." (PMID 32232363, 2020). "Girls with obesity presented a hormonal profile characterized by increased levels of circulating insulin (p < 0.0001), leptin (p < 0.0001), c-peptide (p < 0.0001), amylin (p = 0.0018), glucagon (p = 0.0195), and glucagon-like peptide-1 (GLP-1, p = 0.0001), relative to eutrophic controls." (PMID 33644105, 2020). "Therefore, impaired glucose sensing by COP may result in overeating, reduced energy expenditure, impaired suppression of glucagon secretion, and reduced insulin secretion, which eventually lead to obesity and even type 2 DM." (PMID 28969020, 2017). "However, whether this dysregulation in glucagon secretion is because of obesity and/or diabetic state is relatively unknown in felines." (PMID 28376869, 2017). "Finally, we selected one more unannotated SNP (rs183433761) within the TBP-binding site of the promoter of the human GCG gene of glucagon because this SNP's association with obesity has not yet been examined." (PMID 26694100, 2015). "The mechanism for glucagon's blunted secretion in obesity after hemorrhage is unknown." (PMID 25472607, 2014). "Hyperglucagonemia is observed in obesity, with studies reporting higher fasting and post-MMT or post-OGTT glucagon levels correlated with BMI." (PMID 41575482, 2026). "Obesity results in lower concentrations of GLP-1, PYY, and ghrelin, whereas insulin and glucagon are increased." (PMID 41043686, 2025). "Unmeasured confounders (e.g., cortisol, glucagon, insulin) or residual thyroid-independent effects may contribute, though our adjustments for metabolic proxies (which correlate with insulin resistance and hormonal dysregulation) e.g. obesity, lipids, and thyroid autoimmunity, mitigate some concerns." (PMID 40600010, 2025).